PGRMC2 (progesterone receptor membrane component 2)
Description:
Required for the maintenance of uterine histoarchitecture and normal female reproductive lifespan (By similarity). May serve as a universal non-classical progesterone receptor in the uterus (Probable). Intracellular heme chaperone required for delivery of labile, or signaling heme, to the nucleus (By similarity). Plays a role in adipocyte function and systemic glucose homeostasis. In brown fat, which has a high demand for heme, delivery of labile heme in the nucleus regulates the activity of heme-responsive transcriptional repressors such as NR1D1 and BACH1 (By similarity).
Synonyms: DG6; PMBP
Tractability: Antibody: UniProt places it where antibodies can reach, with high confidence; UniProt predicts a signal peptide or a membrane-spanning region; its Gene Ontology location is reachable by antibodies, with medium confidence; the Human Protein Atlas places it where antibodies can reach. PROTAC: ubiquitination databases record sites on it; its protein half-life has been measured.
Gene: Protein-coding gene on chromosome 4 (128,269,237 to 128,288,829, reverse strand). Ensembl gene ENSG00000164040.
Subcellular location: Membrane; Nucleus envelope; Endoplasmic reticulum; Secreted
Subcellular location (Human Protein Atlas): Cytosol; Nuclear bodies; Plasma membrane; Predicted to be secreted
Pathways (Reactome):
Signal Transduction: RAC2 GTPase cycle; RAC3 GTPase cycle; RHOA GTPase cycle; RHOD GTPase cycle; RHOG GTPase cycle
Cellular responses to stimuli: Heme signaling
Gene Ontology:
Molecular function: heme binding; protein binding; nuclear steroid receptor activity; steroid binding; heme transmembrane transporter activity
Biological process: adipose tissue development; heme transport; nuclear receptor-mediated steroid hormone signaling pathway
Cellular component: endoplasmic reticulum; extracellular region; membrane; nuclear envelope; nucleoplasm; glutamatergic synapse; synapse
Genetic constraint (gnomAD): Loss-of-function variants: 2 observed, 7.42 expected, observed/expected ratio (o/e) 0.27, 90% interval 0.11 to 0.85. That is too few expected variants to judge how well the gene tolerates losing a copy. Missense variants: 154 observed, 151.45 expected, observed/expected ratio (o/e) 1.02, 90% interval 0.89 to 1.16. Synonymous variants: 96 observed, 67.38 expected, observed/expected ratio (o/e) 1.42, 90% interval 1.21 to 1.69.
Homologues: Orthologues: chimpanzee PGRMC2 (99% identical), macaque PGRMC2 (98% identical), dog PGRMC2 (96% identical), pig PGRMC2 (96% identical), guinea pig PGRMC2 (96% identical), mouse Pgrmc2 (88% identical), rat Pgrmc2 (87% identical), zebrafish pgrmc2 (61% identical), tropical clawed frog pgrmc2 (61% identical), Drosophila melanogaster MSBP (44% identical), Caenorhabditis elegans vem-1 (30% identical), Drosophila melanogaster CG16957 (27% identical). Paralogues in human: PGRMC1 (45% identical), CYB5D2 (23% identical), VMP1 (17% identical).
Diseases named in the same sentence as PGRMC2 in open-access papers:
PGRMC2 is named in the same sentence as 30 diseases in open-access papers, as found by Europe PMC text mining. Sharing a sentence is not in itself a finding about the gene and the disease. The quoted sentences say what the papers report.
breast carcinoma (6 papers, 2018 to 2023). "Note also that important genes distinguishing between cancer subtypes, e.g., for breast cancer, like ERBB2 (HER2), ESR1 (ER), and two forms of membrane component of PR, PGRMC1 and PGRMC2, survived shambhalization." (PMID 37745690, 2023). "Additionally, this new cohort demonstrated that increased expression of PGRMC2 also resulted in decreased OS rates in Luminal-A breast cancers that were not previously identified." (PMID 35971177, 2022).
endometriosis (6 papers, 2013 to 2023). The growth of functional endometrial tissue in anatomic sites outside the uterine body. "Furthermore, reduced levels of membrane-bound PGRMC2 may be associated with the progesterone insensitivity often observed in the endometrium of primates afflicted with endometriosis." (PMID 35406659, 2022). "Decreased expression of PGRMC1 and PGRMC2 has been reported in the eutopic endometrium of patients with endometriosis compared to the endometrium of healthy women." (PMID 35956024, 2022). "In contrast, the level of PGRMC2 is reduced and its cellular localization disrupted in a primate model of endometriosis." (PMID 24065879, 2013). "Indeed, reduced levels and abnormal intracellular localization patterns of PGRMC2 in the endometrium of primates (macaques) afflicted with advanced endometriosis were also observed." (PMID 33411206, 2021). "This suggests that aberrant PGRMC2 expression may contribute to P4 refractoriness commonly found in endometriosis." (PMID 24065879, 2013). "Thus, abnormal expression and/or intracellular localization of PGRMC2 may contribute to the blunted response to P4, leading to abnormal endometrial function and decreased fertility observed in subjects with endometriosis." (PMID 33411206, 2021). "The observation of reduced PGRMC2 is in accord with those reported in a non-human primate model of endometriosis, while only humans with endometriosis appear to also exhibit reduced PGRMC1 expression." (PMID 35406659, 2022). "A decrease in the expression and protein content of other membrane progesterone receptors, PGRMC1 and PGRMC2, has also been reported in the eutopic endometrium of patients with endometriosis compared to women without the disease." (PMID 32733932, 2020). "Furthermore, decreased expression level of PGRMC2 may be related to the progesterone insensitivity often observed in the endometrium of non-human primates with endometriosis." (PMID 35956024, 2022). "Compared to controls, macaques with endometriosis exhibited no changes in the expression or localization patterns for PGR and PGRMC1, but exhibited strikingly reduced levels of PGRMC2 transcript and altered intracellular staining patterns for the PGRMC2 protein." (PMID 35406659, 2022).
ovarian carcinoma (4 papers, 2016 to 2025). A malignant neoplasm originating from the surface ovarian epithelium. "As with PGRMC1, PGRMC2 is elevated in ovarian cancer and a large number of ovarian cancer cell lines." (PMID 40227710, 2025). "The relationship between the expression profile of PGRMC1 and PGRMC2 and ovarian cancer is complex because expression and cellular location vary with the subtype of ovarian cancer and the stage of progression." (PMID 34885064, 2021). "Not only are PGRMC1 and PGRMC2 expressed in ovarian cancer, but the nuclear progesterone receptor (PGR) is also expressed." (PMID 34885064, 2021). "Whether the abilities of PGRMC1 and PGRMC2 to influence the composition of the ribosomes and thereby which RNAs get translated into specific proteins changes at different stages of ovarian cancer remains to be determined." (PMID 34885064, 2021). "These genes encode proteins that function as intracellular chaperones and could direct the subcellular distribution of PGRMC1 and PGRMC2 and likely contribute to ovarian cancer progression." (PMID 34885064, 2021). "As with ovarian cancers, miR-21 levels in endometrial cancers are on average 2-fold higher than in benign tissue, which is consistent with the concept that elevated miR-21 in the presence of low levels of PGRMC2 promotes migration of both ovarian and endometrial cancers." (PMID 34885064, 2021). "Previous studies have demonstrated that in an ovarian cancer cell line, SKOV-3 cells, PGRMC1, and PGRMC2 interact with tubulin to regulate the stability of the mitotic spindle." (PMID 34885064, 2021). "Our present observations on the P4 receptor expression pattern in CRC are consistent with the recently reported marginal expression of PGR, with low expression levels of mPRβ, mPRγ, and PGRMC2, and abundant expression levels of PGRMC1 in high-grade human ovarian cancer." (PMID 37894441, 2023). "It has been reported that PGRMC2 interacts with PGRMC1 as a heterodimer in an exogenous expression system in human ovarian carcinoma cells, but homodimerisation of PGRMC2 has not been shown yet." (PMID 27754849, 2016). "Similarly depleting PGRMC2 but not PGRMC1 also increases ovarian cancer cell migration." (PMID 34885064, 2021).
endometrial cancer (2 papers, 2021 to 2025). Primary or metastatic malignant neoplasm involving the endometrium (mucous membrane that lines the endometrial cavity). "The ablation of Pgrmc2 clearly attenuated the incidence/development, progression, and aggressiveness of Pten loss-of-function-induced endometrial cancer by inhibiting endometrial glandular epithelial cell proliferation." (PMID 40227710, 2025). "The ablation of Pgrmc2 on a Pten+/d background also decreased the incidence of endometrial cancer to 7.1% compared to the 22.2% in Pten+/d mice." (PMID 40227710, 2025). "The actions of PGRMC2 are consistent with prior studies in which PGRMC1 knockdown in endometrial cancer cells dramatically reduced xenograft tumor growth in immunocompromised mice while also elevating chemosensitivity." (PMID 40227710, 2025). "Given the lack of in vivo information about a role for PGRMC2 in oncogenesis, we sought to determine if endometrial Pgrmc2 ablation would impact the development and progression of endometrial neoplasia in a well-established model of endometrial cancer." (PMID 40227710, 2025). "The ablation of Pgrmc2 reduced the percentage of Pten+/d mice developing hyperplasia by about 50% and those developing endometrial cancer by 66%." (PMID 40227710, 2025). "In contrast, 100% of Ptend/d; Pgrmc2d/d mice survived to nine months despite all developing endometrial cancer suggesting the Pgrmc2 not only attenuates tumor growth, but also the likely metastatic spread." (PMID 40227710, 2025). "A role for PGRMC2 in the development and progression of endometrial cancer was also assessed using a genetic approach in vivo." (PMID 34885064, 2021). "The level of PGRMC2 protein was evaluated by immunohistochemistry in human endometrial samples during the proliferative and secretory phases of the menstrual cycle, as well as in endometrial cancer specimens." (PMID 40227710, 2025). "However, whereas all Ptend/d mice had to be euthanized prior to the end of the study at nine months, 100% of Ptend/d; Pgrmc2d/d mice survived to nine months of age, suggesting that the ablation of Pgrmc2 attenuated the progression of endometrial cancer." (PMID 40227710, 2025). "PGRMC2 seemed more abundant in the neoplastic epithelium of endometrial cancer tissues when compared to adjacent stromal tissue, but this may likely be due to the presence of stratified epithelium in this neoplastic tissue." (PMID 40227710, 2025). "The objective of this review is to provide an overview of what is known about the roles that PGRMC1 and PGRMC2 play in ovarian and endometrial cancers, particularly as related to the mechanisms through which they regulate mitosis, apoptosis, chemoresistance, and cell migration." (PMID 34885064, 2021). "Whether this PGRMC1/PGRMC2-dependent pathway functions to regulate the proliferation of ovarian and endometrial cancer cells remains to be determined." (PMID 34885064, 2021). "PGRMC2 expression was not different between endometrial cancer tissue compared with endometrial tissue obtained during the proliferative and secretory phase of the menstrual cycle." (PMID 40227710, 2025). "Although focusing on ovarian and endometrial cancer, we will also present data obtained from normal ovarian and uterine cells as well as cell lines in order to provide more detailed information related to the mechanisms of action of PGRMC1 and PGRMC2." (PMID 34885064, 2021). "Interestingly, the epithelial cells of the endometrial cancer samples express elevated levels of both PGRMC1 and PGRMC2 in a manner that more closely mimics that of samples obtained from the proliferative phase of the menstrual cycle." (PMID 34885064, 2021).
adenomyosis (1 paper, 2022). The growth of endometrial tissue inside the muscular wall of the uterine corpus. "The protein expression of PGR, mPRα, mPRβ, and PGRMC1 was significantly higher in adenomyosis compared to the normal myometrium (Figure A1a–c,e), while mPRγ and PGRMC2 had similar expression in both tissues (Figure A1d,f)." (PMID 35956024, 2022).
brain infarction (1 paper, 2023). Tissue necrosis in any area of the brain, including the cerebral hemispheres, the cerebellum, and the brain stem. "The present findings are the first demonstration that the gain‐of‐function of PGRMC2 in mice can reduce brain infarction and acute sensorimotor deficits after ischemic stroke." (PMID 36794556, 2023).
Cerebral ischemia (1 paper, 2023). Restriction of arterial blood supply to the brain associated with insufficient oxygenation to support the metabolic requirements of the tissue. "Progesterone receptor membrane component 2 (PGRMC2) was expressed in different neural cells in the setting of cerebral ischemia." (PMID 36794556, 2023). "Collectively, the findings presented here are the first to support an elevated expression of PGRMC2 in different neural cells in the setting of cerebral ischemia." (PMID 36794556, 2023).
cervical carcinoma (1 paper, 2016). A carcinoma arising from either the exocervical squamous epithelium or the endocervical glandular epithelium. "The same PGRMC2 immunostaining pattern was observed in human cervical carcinoma (HeLa) and human fibroblasts (respectively)." (PMID 27754849, 2016).
chronic obstructive pulmonary disease (1 paper, 2017). A chronic and progressive lung disorder characterized by the loss of elasticity of the bronchial tree and the air sacs, destruction of the air sacs wall, thickening of the bronchial wall, and mucous accumulation in the bronchial tree. "rs116624278 is an intergenic SNP located between PGRMC2 and JADE1 genes, in a QTL for chronic obstructive pulmonary disease, heart rate and osteoarthritis." (PMID 28152013, 2017).
ciliopathy (1 paper, 2020). A genetic disorder of the cellular cilia or the cilia anchoring structures, the basal bodies, or of ciliary function. "The regulation of TMEM216 expression by F11R and PGRMC2 may partially explain the ciliopathy phenotypes seen in zebrafish model." (PMID 32832346, 2020).
colon cancer (1 paper, 2022). "We speculate that among the three downregulated genes more closely related to colon cancer, PGRMC2 is associated with the progression of a variety of tumors but no related reports have been found in colon cancer." (PMID 35845138, 2022).
dyslipidemia (1 paper, 2021). "Additionally, the expression of EPGN, LGR5, NCK1, PGRMC2, and VIP were also comfired at transcriptional using qPCR, indicating that those genes are closely linked to dyslipidemia in OSA." (PMID 34880901, 2021).
epilepsy (1 paper, 2024). A brain disorder characterized by episodes of abnormally increased neuronal discharge resulting in transient episodes of sensory or motor neurological dysfunction, or psychic dysfunction. "We used WB technology to detect the protein expression of PGRMC2 in the hippocampus of CON and chronic epilepsy model mice." (PMID 39346797, 2024). "We detected the distribution and localization of PGRMC2 in CON and epilepsy group brain tissues by the immunofluorescence technique." (PMID 39346797, 2024).
epileptic seizures (1 paper, 2024). "Therefore, we speculate that PGRMC2 is involved in the occurrence and development of epileptic seizures, but the mechanism through which PGRMC2 affects the occurrence and development of epileptic seizures is unknown and needs further exploration." (PMID 39346797, 2024).
hemochromatosis (1 paper, 2023). A disorder of iron metabolism characterized by a triad of HEMOSIDEROSIS; LIVER CIRRHOSIS; and DIABETES MELLITUS. "Consequently, S1R, S2R, PGRMC1, and PGRMC2 potentiate disease progression in hemochromatosis and cancer." (PMID 37834119, 2023).
Hydrocephalus (1 paper, 2020). Hydrocephalus is an active distension of the ventricular system of the brain resulting from inadequate passage of CSF from its point of production within the cerebral ventricles to its point of absorption into the systemic circulation. "Although some variation and severity were observed, knockdown of the corresponding six genes (BMPR2A, BMPR2B, TFRC, F11R, PTPRS, and PGRMC2) resulted predominantly in ciliopathic disorders, including abnormal development, hydrocephalus, kidney cysts, and left–right asymmetry in cardiac looping." (PMID 32832346, 2020).
ischemic stroke (1 paper, 2023). A stroke disorder caused by obstruction of blood flow to the brain, due to thrombotic (local blood clot formation) or embolic (due to a blood clot or other material traveling from another site) event. "The present findings showed that the gain‐of‐function of PGRMC2 reduced Evans blue extravasation, brain edema, and brain water content that accompanies ischemic stroke." (PMID 36794556, 2023). "This study provides the first evidence that PGRMC2 is significantly elevated in different neural cells in the setting of ischemic stroke." (PMID 36794556, 2023). "We also examined BBB leakage/permeability, sensorimotor dysfunctions, astrocyte activation, microglial activation, neuronal death/apoptosis, and synaptic plasticity after MCAO and CPAG‐1 treatment to explore the role of PGRMC2 in ischemic stroke." (PMID 36794556, 2023). "Progesterone receptor membrane component 2 was elevated in different brain cells after ischemic stroke." (PMID 36794556, 2023). "We also achieved significant protective neuropathological and neurobehavioral effects by intraperitoneal injection of CPAG‐1, a gain‐of‐function ligand of PGRMC2, in our murine model of ischemic stroke." (PMID 36794556, 2023). "The present study sought to determine the regulatory role of PGRMC2 in ischemic stroke." (PMID 36794556, 2023). "However, the role of PGRMC2 in ischemic stroke remains unexplored." (PMID 36794556, 2023). "The regulatory role of PGRMC2 in glial cell activation, BBB permeability, neuronal survival, and recovery of sensorimotor dysfunctions in the setting of ischemic stroke is still unclear." (PMID 36794556, 2023). "The intraperitoneal injection of CPAG‐1, a gain‐of‐function ligand of PGRMC2, conferred resistance to BBB leakage, astrocyte activation, microglial activation, neuronal death, and disruption of neuroplasticity while promoting the recovery of sensorimotor dysfunctions after ischemic stroke." (PMID 36794556, 2023). "This indicated that PGRMC2 was mainly expressed in neuronal cells, astrocytes, and microglia under physiological conditions, and that its levels were elevated in neuronal cells and astrocytes, but not microglia following ischemic stroke." (PMID 36794556, 2023).
lentivirus infection (1 paper, 2020). Virus diseases caused by the Lentivirus genus. "The lentivirus infection was first verified using non‐GFP scrambled and GFP‐tagged PGRMC2 or F11R‐targeted shRNA." (PMID 32832346, 2020).
osteoporosis (1 paper, 2025). A condition of reduced bone mass, with decreased cortical thickness and a decrease in the number and size of the trabeculae of cancellous bone (but normal chemical composition), resulting in increased fracture incidence. "Additionally, abnormal expression of PGRMC2 has been found to be associated with osteoporosis risk, potentially participating in the regulation of the bone immune microenvironment by influencing the differentiation process of monocytes into macrophages." (PMID 41229417, 2025). "Genetic analysis further supports the protective role of PGRMC2 in osteoporosis." (PMID 41229417, 2025).
ovarian tumors (1 paper, 2021). "Searching this database (July 2021) revealed that both mRNA and protein levels of PGRMC1 and PGRMC2 are significantly elevated in ovarian tumors." (PMID 34885064, 2021).
prostate carcinoma (1 paper, 2021). A carcinoma that arises from epithelial cells of the prostate gland. "In addition, we analyzed the expression levels of PGR, PGRMC1, and PGRMC2 genes in prostate cancers." (PMID 34572596, 2021).